SIRT7 (sirtuin 7)
Diseases named in the same sentence as SIRT7 in open-access papers (continued):
Sharing a sentence is not in itself a finding about the gene and the disease.
cardiovascular disease (5 papers, 2021 to 2025). "Elderly patients with cardiovascular disease and deficiency of plasma selenium, a trace mineral that enhances antioxidant capacity and influences inflammatory signaling pathways, showed low levels of SIRT7 in peripheral blood mononuclear cells (PBMCs)." (PMID 35585284, 2022). "It is worth noting that most previous studies regarding SIRT7 and cardiovascular diseases have been concentrated at the animal level." (PMID 40884727, 2025). "Short-term CR increases expression of SIRT1-4 and SIRT7 in cardiomyocytes, which demonstrates the beneficial effect that diet can have on cardiovascular disease progression." (PMID 33806509, 2021). "In cardiovascular disease, SIRT7 exhibits a dual regulatory role." (PMID 40884727, 2025). "Diet (CR) inhibits cardiovascular disease progression by increasing expression of SIRT4 and SIRT7." (PMID 33806509, 2021).
infection (4 papers, 2017 to 2025). The state of being infected such as from the introduction of a foreign agent such as serum, vaccine, antigenic substance or organism. "The k-means clustering analysis further revealed the expression pattern shift of key gene clusters regulating GPS infection is due to SIRT7 deficiency." (PMID 40636259, 2025). "In this study, to investigate SIRT7’s regulatory role during GPS infection, we first constructed SIRT7 deficiency 3D4/21 cell lines using CRISPR/Cas9 gene editing technology." (PMID 40636259, 2025). "In our study, SIRT7 deficiency significantly suppressed cytopathy and inflammation induced by GPS infection." (PMID 40636259, 2025). "To systematically characterize SIRT7-regulated key gene clusters during GPS infection, we identified overlapping DEGs between SIRT7-KO and WT cells under both basal and infected conditions." (PMID 40636259, 2025). "Our results showed that GPS infection upregulates SIRT7 expression in macrophages suggests its potential involvement in antibacterial defense mechanisms." (PMID 40636259, 2025). "We found that SIRT7 expression is significantly decreased duringMtb infection in mRNA expression and protein levels." (PMID 39287444, 2024). "We foundthat, compared to wild-type (Sirt7+/+) mice,Sirt7−/− mice showed increasedbacterial burden in lungs and spleens at both 4 and 8 weeks post-infection withH37Rv." (PMID 39287444, 2024). "Aligning with their findings, we alsoobserved the downregulation of SIRT7 expression in macrophages duringMtb infection." (PMID 39287444, 2024). "We showed that SIRT7-mediatedRAC1 activation promoted cytoskeletal remodeling and innate responses duringMtb infection." (PMID 39287444, 2024). "SIRT7 expression was quantified by real-time PCR and western blotting analysis 3 days after infection and screening." (PMID 28880264, 2017). "Western blot analysis found that the protein expression of SIRT7 was significantly upregulated during GPS infection, indicating that SIRT7 may participate in GPS-induced inflammatory response." (PMID 40636259, 2025). "This suggests that SIRT7 may interact with these hub genes to regulate inflammation response or ribosome biogenesis for affecting GPS infection." (PMID 40636259, 2025). "Here we found that GPS infection increased SIRT7 expression and induced inflammatory responses." (PMID 40636259, 2025). "It was found that SIRT7-KO cells showed less cell damage infection, and significantly reduced expression of pro-inflammatory cytokines (IL-6, IL-8, TNF-α) upon GPS infection, suggesting that SIRT7 deficiency can suppress the occurrence of inflammation induced by GPS infection." (PMID 40636259, 2025). "Collectively, these resultssupport the hypothesis that SIRT7 has a protective role in defenses againstMtb infection." (PMID 39287444, 2024). "In summary, our results demonstrate that SIRT7 is pivotal for GPS-induced inflammatory responses, which represents a promising target resistant to GPS infection." (PMID 40636259, 2025). "Flow cytometry analysis of BCG-GFP-infected cells 24h after infection and CFU counts of H37Rv-infected cells 48h after infection revealed that SIRT7 knockdown macrophages had higher bacillary loads compared with those of the control cells (–D)." (PMID 34925356, 2021). "SIRT7 is an NAD+-dependent deacetylase known to regulate inflammatory responses, but its role in GPS infection remains unclear." (PMID 40636259, 2025). "Newcastle disease virus infection induced SIRT7 expression, which in turn enhances cellular proteins deacetylation causing high virus replication.However, the regulatory mechanism of the SIRT7 gene in GPS infection has not yet been reported." (PMID 40636259, 2025). "Therefore, we concluded that SIRT7, in its role regulatingcytoskeletal remodeling through RAC1, is critical for host responses duringMtb infection and proposes a potential target fortuberculosis treatment." (PMID 39287444, 2024).
infection (continued). "A time-dependent reduction in SIRT7 mRNA expression was observed in Raw264.7 cells infected with the Mtb virulent strain H37Rv, while there were no significant changes in SIRT2 mRNA expression before and after infection." (PMID 34925356, 2021). "Notably, PI3K-Akt signaling and tight junction pathway showed specific enrichment in SIRT7-KO cells without infection compared to WT cells." (PMID 40636259, 2025).
inflammation (4 papers, 2022 to 2025). Aberrant reaction of the microcirculation characterized by movement of fluid and leukocytes from the blood into extravascular tissues. "To further determine the role of RELA deacetylation mediated by SIRT7 in largemouth bass, we established a LPS-induced fish model with acute liver inflammation and isolated primary hepatocytes followed by LPS stimulation." (PMID 41322258, 2025). "Our study demonstrated that SIRT7 inhibition blocks the inflammatory response in the colon of mice, suggesting a possible role for SIRT7 in the pathogenesis of immune-mediated intestinal inflammation." (PMID 36359214, 2022). "Besides, depletion of SIRT7 inhibits LPS‐induced endothelial inflammation in acute lung injury." (PMID 39092715, 2024).
bladder (3 papers, 2015 to 2022). "To gain additional mechanistic insight into the role of SIRT7 in theinvasion-metastasis cascade, we first focused on the effects of SIRT7inactivation in epithelial carcinoma cells." (PMID 25923013, 2015). "Additionally, significantly decreased SIRT7 expression was also observed in IHG compared to papillary high-grade carcinomas (PHG)." (PMID 32344886, 2020). "Overall, lower transcript levels were observed in invasive high-grade carcinomas (IHG) comparing with papillary low-grade carcinomas (PLG), although statistical significance was only reached for SIRT7 (KW p < 0.0001)." (PMID 32344886, 2020).
central nervous system tumors (1 paper, 2025). "Collectively, these mechanisms underscore a mitochondria-directed role of SIRT7 in quality control, translational tuning of mitochondrial protein synthesis, and metabolic stress adaptation—all potentially relevant in CNS tumor biology." (PMID 40710366, 2025).
heart disease (1 paper, 2022). "SIRT7 used to be the least studied sirtuin, but some research breakthroughs have confirmed that SIRT7 has important biological functions and is associated with a variety of diseases, including heart disease, fatty liver, and many types of tumors." (PMID 35677446, 2022).
SIRT7 also shares sentences with these, for which no sentence is quoted: fatty liver (8 papers); cholangiocarcinoma (4); Cerebral ischemia (2); digestive system diseases (2); gastric tumor (2); ischemia (2); nervous system diseases (2); neurodegenerative disease (2); nevus (2); prostate tumor (2); renal cell carcinoma (2); Acidosis (1); acute myocardial infarction (1); age-related hearing loss (1); alcoholic liver diseases (1); Alzheimer disease (1); anaplastic thyroid cancer (1); benign prostatic hyperplasia (1); bladder urothelial carcinoma (1); carcinoid tumor (1); cerebral infarction (1); chronic heart failure (1); clear cell renal cell carcinoma (1); colon adenocarcinoma (1); diabetic cardiomyopathy (1); esophageal cancer (1); fibrosis (1); gastric adenocarcinoma (1); hepatitis B (1); Huntington disease (1).
A further 30 diseases each share a sentence with SIRT7 in 1 paper.